STAT3 (signal transducer and activator of transcription 3)
Diseases named in the same sentence as STAT3 in open-access papers (continued):
Sharing a sentence is not in itself a finding about the gene and the disease.
gastric cancer (continued). "Autocrine and paracrine interleukin (IL)-6 signaling is the principal mechanism by which Stat3 is persistently phosphorylated in epithelial tumors including breast, lung, colon and gastric cancer." (PMID 20929542, 2010). "Taken together, these findings suggested that SOCS-1 play an important role in the inhibition of IL-6-mediated STAT3 activation in AGS gastric cancer cell line." (PMID 15354212, 2004). "In gastric cancer, STAT3 regulates ferroptosis primarily through its own histone acetylation, which increases its gene-level expression and promotes the expression of downstream direct targets GPX4, SLC7A11, and FTH1, thereby exerting an anti-ferroptotic effect." (PMID 41513612, 2026). "GlyGCC-001-N-5i-1-33 was shown to inhibit STAT3 in gastric cancer." (PMID 40981380, 2025). "IL-6 is frequently elevated in human gastric cancer and activates STAT3 signaling to promote proliferation, survival, and metastasis; the modest protective effect of IL-6 deletion suggests that other cytokines may compensate for its loss in this model." (PMID 40673273, 2025). "LncRNA-CCAT5 is a direct transcriptional target of the WNT signaling cascade, and lncRNA-CCAT5 is significantly upregulated in gastric cancer and plays a role in promoting the growth and metastasis of gastric cancer in a STAT3-mediated manner, suggesting a poor prognosis." (PMID 40296904, 2025). "Interestingly, increased C3 expression was shown to trigger the JAK/STAT3 pathway in gastric cancer, which led to a subsequent increase in cell proliferation." (PMID 40698088, 2025). "Other studies demonstrated that miR-21 promotes STAT3-dependent gastric cancer progression." (PMID 40746848, 2025). "In vitro, conditioned media from LPS-activated macrophages accelerates gastric cancer cell growth and triggers concurrent NF-κB/STAT3 activation via inhibitor of kappa B alpha (IκBα) degradation and JAK2 phosphorylation, while also reshaping the tumor epigenome." (PMID 41373680, 2025). "Crosstalk with macrophages further reinforces this state: CAF-derived chemokines attract and polarize myeloid cells that, in turn, sustain STAT3/NF-κB-driven inflammation and release additional MMPs, a pattern reproduced in gastric cancer cell–macrophage systems." (PMID 41373680, 2025). "Notably, our research offers the first proof that DZN and PNR together operate as an anti-cancer drug by blocking MMP-2 production in human gastric cancer cells through the STAT3/FAK signalling pathways." (PMID 40217305, 2025). "Several previous studies also indicated that STAT3 might represent a novel therapeutic target in gastric cancer." (PMID 41280323, 2025). "Overexpressed C3 could activate JAK2/STAT3 pathway, which has a correlation with the progression of gastric cancer." (PMID 40396123, 2025). "In gastric cancer, NOX2 has been found to be highly expressed in tumor tissues, and the NOX2-ROS axis can mediate the activation of tumorigenesis-associated pathways, including the Akt-mTOR, Stat3, and NF-κB signaling pathways." (PMID 41441930, 2025). "SCIN enhances the progression of gastric cancer by modulating STAT3 and NF‐Κb signaling pathways." (PMID 39964147, 2025). "All of these findings point to the possibility that using DZN and PNR to target the STAT3 signalling pathway could be a successful therapy or preventative approach for gastric cancer." (PMID 40217305, 2025). "For example, JAK/STAT3 inhibitors are under development and have shown early promise in gastric cancer patients, and FOXM1 inhibitors or cell cycle modulators could potentially be explored to specifically curb the proliferative drive in PGC." (PMID 40862793, 2025). "Additionally, a mouse study on gastric tumorigenesis induced by N-methyl-N-nitrosourea revealed that IL-6 promotes gastric cancer cell proliferation through the activation of STAT3, as demonstrated by comparing IL-6 knockout mice with wild-type mice." (PMID 40051564, 2025).
gastric cancer (continued). "According to multiple findings, triggers of STAT3 may be utilized as a molecular grading indicator for determining a bad prognosis for gastric carcinoma and related to the disease's growth and invasiveness." (PMID 40350446, 2025). "The STAT3 protein plays a pivotal role in the proliferation and development of gastric cancer." (PMID 39309860, 2024). "TANs activate the JAK2/STAT3 pathway in gastric cancer cells by secreting interleukin-17a (IL-17a)." (PMID 39050856, 2024). "Thus, the coapplication of Met and STAT3 inhibitors can minimize resistance and enhance treatment efficacy in gastric cancer." (PMID 39309860, 2024). "Alternative signaling routes that gastric cancer cells may use when STAT3 is inhibited need to be further investigated." (PMID 39309860, 2024). "The inhibition of the Notch and STAT3 pathways may increase the therapeutic potency of trastuzumab against gastric cancer and prevent the development of treatment resistance." (PMID 39309860, 2024). "Our results showed that salidroside significantly down-regulated the expression of MAP3K6 and STAT3 genes in gastric cancer cells, indicating that salidroside suppressed the proliferation and progression of gastric cancer cells by inhibiting the expression of these pathway molecules." (PMID 38436092, 2024). "Further exploration revealed that IL-10 may trigger the activation of the c-MET/STAT3 signaling pathway, fueling gastric cancer progression." (PMID 39664377, 2024). "In the future, the combined application of anti-EGFR targeted therapies and STAT3 inhibitors could represent a promising investigational treatment strategy for patients with EGFR-positive gastric cancer." (PMID 39309860, 2024). "Furthermore, we assess recent advances in the development of STAT3 inhibitors and their potential application as therapeutic agents in the treatment of gastric cancer." (PMID 39309860, 2024). "In the subsequent sections, we discuss the involvement of STAT3 in gastric cancer metastasis; this information might serve as a resource for researchers." (PMID 39309860, 2024). "Concerning gastric cancer biology, dopamine has notable effects on STAT-3 and DARPP-32." (PMID 39767693, 2024). "SF8 (terphenyllin) could suppress the growth and metastasis of gastric cancer by inhibiting the STAT3 signaling pathway, also showing significant neuroprotective effects against oxidative stress in Neuro-2a Cells." (PMID 39330395, 2024). "The IL-11/STAT3 axis is crucial for tumorigenesis within the gastric environment, as demonstrated in the gp130757FF mouse model, with similar results found in several murine models of gastric cancer." (PMID 39309860, 2024). "Glycitein could promote apoptosis and cell cycle arrest in the G0/G1 phase of human gastric cancer cells via ROS-related MAPK/STAT3/NF-κB pathways." (PMID 39338323, 2024). "Importantly, the cytokine TGF-β, which has been suggested in several papers to mediate EMT transformation to form CAFs in gastric cancer, can be positively regulated by STAT3." (PMID 39309860, 2024). "Based on the evidence presented, it is suggested that luteolin may have the potential to inhibit STAT3 signaling and thus possess antitumor effects in gastric cancer cells." (PMID 38474604, 2024). "Also, IL-6/STAT3 signaling pathway was reported to play a major role in the progression of gastric cancers." (PMID 38967742, 2024). "Additionally, the expression of CR-1 was found to be positively correlated with p-STAT3 expression in GC, which indicated that CR-1 plays pivotal roles in the emergence and lymphatic spread of gastric cancer (r(k) = 0.189, P = 0.002)." (PMID 39309860, 2024). "Furthermore, in gastric cancer, ACKR3 has been implicated in promoting tumor growth and metastasis via the STAT3/c-Myc pathway." (PMID 38920657, 2024). "The IL-6/STAT3 signaling pathway plays a major role in the progression of gastric cancers." (PMID 38967742, 2024).
gastric cancer (continued). "Additionally, gastric cancer cells overexpressing STAT3 often overexpress EGFR on the cell membrane." (PMID 39309860, 2024). "The administration of propofol arrested the proliferation of the SGC-7901 gastric cancer cell line, which was similar to the results recorded after the upregulation of hsa-miR-328-3p and the reduction in the levels of STAT3 and its downstream proliferative genes." (PMID 39309860, 2024). "Activated JAK1/STAT3 is crucial in gastric cancer proliferation and metastasis." (PMID 39136000, 2024). "It is commonly acknowledged that JAK2/STAT3 has a role in the development of gastric cancer." (PMID 38305998, 2024). "Moreover, EXOSC5 expression has been linked to an increase in cyclin D1 and a decrease in p21/p27 expression, which promotes cell proliferation through the regulation of the AKT/STAT3 pathway in gastric cancer." (PMID 38164180, 2024). "We hypothesize that STAT3 may facilitate the development of EGFR-positive gastric cancer and contribute to drug resistance through interactions with molecules such as DARPP-32 and FGD5, possibly involving other yet-to-discovered mechanisms." (PMID 39309860, 2024). "Shoumin Zhu and colleagues conducted a series of in vitro assays and 3D gastric organoid cultures using mouse models and human tissues to determine the effect of DARPP-32 on the activation of IGF1R and STAT3 signaling, which is crucial for the onset of gastric cancer." (PMID 39309860, 2024). "Finally, we confirmed tumor cell–intrinsic Yap1 expression as tumor-promoting mechanism outside a Stat3-driven model (i.e., Gp130FF), also in a bona fide oncogene–driven gastric cancers model." (PMID 37957015, 2024). "STAT3 knockdown in gastric cancer cells provoked a significant inhibition of GPX4, SLC7A11, and FTH1 at both the mRNA and protein levels, and also increased lipid peroxidation and ROS, and enhanced intracellular Fe2+, thus reducing the GSH/GSSG ratio in gastric cancer cells." (PMID 38539832, 2024). "A previous study demonstrated that STAT3 directly upregulated Toll-like receptor 2, an inflammatory mediator, to inhibit epithelial proliferation and anti-apoptosis, thereby enhancing tumorigenesis instead of inflammation in gastric cancer." (PMID 38273295, 2024). "Blocking STAT3 can activate ferroptosis in these cells by increasing lipid peroxidation and the accumulation of Fe2+; this is an effective strategy to counter 5-FU resistance in advanced gastric cancer patients." (PMID 39309860, 2024). "According to the findings of the study, the anti-tumorigenic impact of pantoprazole may be mediated via the modification of the SHP-1/p-STAT3 axis in the context of gastric cancer." (PMID 39507107, 2024). "Therefore, the blockade of STAT3 by inhibitors is a promising therapeutic agent for tumorigenesis and metastasis in gastric cancer, breast cancer, and thyroid cancer." (PMID 39507759, 2024). "Antagonizing STAT3 and blocking Sp1 binding sites could inhibit the proliferation of gastric cancer cells." (PMID 39309860, 2024). "DARPP-32, a protein involved in tumorigenesis, demonstrated that, in its transient form, it increases STAT-3 expression in human gastric carcinoma epithelial cell line (AGS) cells, while in the endogenous form, this protein has the opposite effect in MKN-45 cells." (PMID 39767693, 2024). "This is attained byinhibiting the process of STAT3 translocation, access to nucleus and combination with VEGF promoter in gastric carcinoma, as well as the inhibition of VEGF protein level, secretion, and mRNA expression due to reduced activation of STAT3 in gastric carcinoma." (PMID 38611849, 2024). "However, the levels of p-JAK2, a key molecule upstream of p-STAT3, were higher in the gastric cancer cell lines than in the normal gastric epithelial cell line GES-1." (PMID 36672337, 2023).
gastric cancer (continued). "Furthermore, PA inhibited the nuclear localization of p-STAT3, indicating its potential to inhibit the proliferation and metastasis of gastric cancer cells by suppressing the JAK2/STAT3 immune signaling pathway." (PMID 37637038, 2023). "Similarly, after analyzing 255 human gastric cancer specimens immunohistochemically, one study noticed a significantly positive correlation between NF-κB and STAT3 activation." (PMID 37508393, 2023). "In addition, our study demonstrated that GDF15 is involved in cell proliferation, migration, and invasion in gastric cancer via STAT3/MYC signaling." (PMID 36769245, 2023). "In addition, IL-6 stimulated gastric cancer stemness by activating the STAT3 signaling pathway and upregulating the stemness-related marker OCT4." (PMID 36838713, 2023). "Among them, INF-γ, IL-17 and IL-21, and B-cell inflammatory genes are significantly increased in people with CAD, and IL-17a promotes the epithelial to mesenchymal transition in gastric cancer cells through JAK2/STAT3, exacerbating the development of gastric cancer." (PMID 36970364, 2023). "Moreover, circ-0000117 promotes the proliferation of gastric cancer cells by inhibiting the miR-337-3p/STAT3 axis." (PMID 37488484, 2023). "Besides, the regulatory role of PGD2 on PPARγ activation and STAT3 phosphorylation was demonstrated in the development of gastric cancer and prostate tumor." (PMID 36725845, 2023). "The present study demonstrated that GDF15-mediated STAT3 activation induced EMT in gastric cancer." (PMID 36769245, 2023). "Moreover, GDF15 promotes cancer progression via the phosphorylation of STAT3 and cell-cycle-related proteins in gastric cancer." (PMID 36769245, 2023). "Therefore, we evaluated the effects of PA on cell proliferation, invasion, and apoptosis in human gastric cancer, as well as the role of p-STAT3 in mediating its effects." (PMID 36672337, 2023). "They suggest that TLR2 is a direct transcriptional target of STAT3; additionally, they draw attention to the data of patients with gastric cancer in whom increased activation of the STAT3 pathway, as well as TLR2 expression, negatively affect the survival of the affected person." (PMID 36982898, 2023). "Besides, IL-6 and TNF-α secreted from macrophages induce PD-L1 expression through NF-κB and STAT3 signaling pathways in gastric cancer cells." (PMID 36978108, 2023). "Moreover, propofol decreased GPX4 and SLC7A11 protein levels by impairing STAT3 expression and slowed gastric cancer growth in vivo." (PMID 36944609, 2023). "Although the expression of p-STAT3 in patients with gastric cancer has been systematically reviewed, the molecular mechanisms underlying STAT3 activation in gastric cancer have not been fully characterized." (PMID 36672337, 2023). "We thus examined whether the blockade of GDF15 affected the STAT3 activation in gastric cancer cells." (PMID 36769245, 2023). "Additionally, propofol was found to decrease GPX4 and SLC7A11 protein levels by suppressing STAT3 expression, decelerating gastric cancer growth in vivo." (PMID 38111578, 2023). "The CXCR2-STAT3 pathway may be involved in angiogenesis in gastric cancer; activated STAT3 increases the expression of VEGF —the most important growth factor that causes angiogenesis." (PMID 37408240, 2023). "For example, high activation of interleukin-6/IL-6 receptor signal transducer and STAT3 signaling pathway was observed in the gastric cancer cells MGC803 and BGC823 treated with CIS in comparison to untreated cells, triggering a CIS-induced CSC-like enrichment." (PMID 36776295, 2023). "In addition, some evidence has investigated that JAK2/STAT3 pathway is involved in the regulation of ferroptosis, such as gastric cancer and head and neck squamous cell carcinoma." (PMID 36814203, 2023). "Furthermore, IL-17 secreted by CAFs upregulates JAK2/STAT3 signaling, which promotes gastric cancer cell malignancy." (PMID 37173977, 2023).
gastric cancer (continued). "In addition, the IL6/JAK/STAT3 pathway was reported to be upregulated in EBV-associated epithelial cancers such as Nasopharyngeal carcinoma, gastric carcinoma, and oral squamous cell carcinoma." (PMID 37297008, 2023). "Suppression of GSDMD expression in gastric cancer can activate the signal transducer and activator of transcription 3 (STAT3) and phosphatidylinositol 3 kinase/protein kinase B (PI3K/PKB) signaling pathways and regulate cell cycle-related proteins to accelerate the S/G2 phase cell transition." (PMID 35990696, 2022). "Among these polyphyllins, PPI has a significant therapeutic effect on hepatocellular carcinoma, CRC, melanoma, prostate cancer, and gastric cancer by inducing cell cycle arrest, apoptosis, and autophagy, as well as by inhibiting the activation of STAT3 and the PI3K/AKT/mTOR signaling pathways." (PMID 36233191, 2022). "Interestingly, we have found decreased phosphorylation of ANXA2 at Y715 and a decrease in phosphorylation of STAT3 upon inhibition of CAMKK2 in gastric cancer cells." (PMID 35646067, 2022). "It has been proved that the down-regulation of GSDMD could promote cell cycle arrest and activate ERK/STAT3/PI3K/AKT pathway in gastric cancer." (PMID 36349258, 2022). "Our study shows that SDL-1 is a potent STAT3 degrader and may serve as a potential anti-gastric cancer drug, providing ideas for further development of drugs for clinical use." (PMID 36034876, 2022). "Thus, SIRT1 has a repressive function on gastric cancer via inhibiting the activation of STAT3 and NF-κB." (PMID 36014536, 2022). "STAT3 expression was upregulated in gastric cancer tissues compared with paracancer tissues." (PMID 36246567, 2022). "SIRT1 could inhibit proliferation and metastasis of gastric cancer cells via the STAT3/MMP-13 signaling pathway." (PMID 36324577, 2022). "STAT3 is found to expedite metastasis and cell proliferation in gastric cancer." (PMID 35322746, 2022). "This indicates that CAMKK2-mediated signaling may orchestrate through PTK2/JUN/STAT3 signaling in gastric cancer." (PMID 35646067, 2022). "In a Balb/c nu/nu tumor transplantation model, CD4+ T cells are reported to upregulate PD-L1 expression in gastric cancer-derived MSCs (GC-MSCs) via the p-STAT3 signaling pathway, and to activate the PD-1/mTOR signaling pathway, thereby promoting gastric cancer growth." (PMID 36439438, 2022). "Many drugs that inhibit STAT3 activation promote apoptosis in gastric cancer cells." (PMID 36038533, 2022). "In gastric cancer, STAT3 occupies the promoter of PVT1 and stimulates PVT1 expression." (PMID 36295083, 2022). "A more detailed understanding about the role of CAMKK2 in activation of the tyrosine phosphoproteome and, in particular, PTK2/JUN/STAT3 signaling in gastric cancer is needed, in addition to functional studies in preclinical models, which is beyond the scope of this article." (PMID 35646067, 2022). "Curcubitacin B suppressed the invasion and proliferation of gastric cancer cells through STAT3 inhibition, which also induced apoptosis and furthermore in combination with cisplatin produced increased cytotoxic effects, which indicate that curcibitacin B is a promising STAT3 inhibitor." (PMID 36500466, 2022). "It has been proven that ERH can combine with Pontin, a highly conserved AAA+ adenosine-triphosphate enzyme (ATPase) family member, to have an effect on serine-phosphorylated STAT3, regulating canonical tyrosine phosphorylation and enhancing transcriptional activity in gastric cancers." (PMID 35677162, 2022). "In gastric cancer, overexpression of p-Stat3 increased sphere formation from CD44+ CSCs." (PMID 35600882, 2022). "Taken together, our results indicated that terphenyllin exerts its anticancer activity by inhibiting the STAT3 signaling pathway and may serve as a potent STAT3 inhibitor for gastric cancer treatment." (PMID 35401187, 2022).